INS (insulin)
Diseases named in the same sentence as INS in open-access papers (continued):
Sharing a sentence is not in itself a finding about the gene and the disease.
type 2 diabetes (continued). "Studies on the effect of various diets on glycemic control in people with type 2 diabetes treated with insulin have not been conducted so far, and thus—are required." (PMID 30871141, 2019). "Another study suggested that healthy children with a family history of type 2 diabetes in comparison to those without it were possibly insulin-resistant." (PMID 30866603, 2019). "Of these patients, 16 were receiving type 1 diabetes treatment (30.2%); 11 were receiving type 2 diabetes treatment without insulin treatment (20.8%); and 26 were receiving type 2 diabetes treatment with insulin (49.0%)." (PMID 31726788, 2019). "Whereas in type 1 diabetic individuals insulin signaling is absent as a result of the lack of insulin synthesis and/or secretion, type 2 diabetes is characterized by impaired, but still active, insulin signaling." (PMID 31212580, 2019). "A signalosome complex of glucokinase, proapoptotic protein, Bcl-2-associated death promoter, BADS, and PKA has been reduced in βIRKO, thus linking the lack of autocrine insulin with the development of type-2 diabetes." (PMID 30450940, 2019). "In Only two distinct studies of GC supplementation, changes of FBS and insulin sensitivity in overweight or obese pre-diabetic women and glycemic indices (FBS, insulin, and HbA1c) among type 2 diabetic patients, were not significant." (PMID 30871514, 2019). "The disease is also characterized by the accumulation of fat in the liver, as adipose tissue lipolysis is not sufficiently inhibited by insulin in type 2 diabetes." (PMID 31222113, 2019). "Physical activity is also known to increase insulin mediated glucose uptake and, in individuals without type-2 diabetes, exercise positively impacts on systemic glucose homeostasis." (PMID 30971232, 2019). "In type 2 diabetic patients, increased expression of the 5-HT2AR was found in unspecified pancreatic islet cells relative to healthy controls, while 5-HT2CR inhibits insulin secretion by beta cells in a diabetic mouse model." (PMID 31367837, 2019). "In type 2 diabetes, hepatic glucose production is higher in the post-absorptive state, and fails to be properly suppressed by insulin, primarily due to the increased rate of gluconeogenesis rather than glycogenolysis." (PMID 31075962, 2019). "Type 2 diabetes occurs when target tissues does not react to insulin effectively, namely insulin resistance." (PMID 30733818, 2019). "We hypothesise that in early type 2 diabetes, BAM will have greater hepatic and adipose tissue insulin sensitivity because of their lower VAT deposition compared with their white European counterparts." (PMID 30729259, 2019). "Therefore, our results suggested that ADLE is a potential therapeutic drug for decreasing hyperlipidemia and improving insulin sensitivity in patients with NAFLD and with type 2 diabetes." (PMID 31277481, 2019). "It is therefore not surprising that NEAT score seems to be associated with amelioration in insulin sensitivity, waist circumference, HDL, blood pressure, and the markers for atherosclerosis in people with type 2 diabetes without hypoglycemic therapy." (PMID 31607950, 2019). "Type II diabetes mellitus (T2DM) is a common chronic disease of the endocrine system in which the pancreas no longer produces enough insulin to metabolize blood glucose or the body becomes less sensitive to insulin (ie, insulin resistance)." (PMID 31588907, 2019). "As decreased beta-cell insulin secretory function plays a central role in both GDM and type 2 diabetes, it is conceivable that rs10830962 might affect beta-cell function in the pathogenesis of GDM." (PMID 30926842, 2019). "Collectively, long-term kisspeptin exposure generally diminished insulin secretion including GSIS, which may lead to the development of type 2 diabetes." (PMID 31767891, 2019).
type 2 diabetes (continued). "Type 1 diabetes (T1D) is characterized by autoimmune destruction of pancreatic β-cells, resulting in a lack of insulin production; whereas type 2 diabetes (T2D) is the result of insulin resistance and usually has a later onset, but is much more prevalent." (PMID 31581464, 2019). "This includes diabetic cardiomyopathy (DbCM), a progressive form of heart disease that occurs with both insulin-dependent (type-1) and insulin-independent (type-2) diabetes and arises in the absence of hypertension or coronary artery disease." (PMID 31214041, 2019). "Women with type 2 diabetes require a much greater increase in insulin dose from the start to the end of each trimester, and insulin requirements do not decrease in early and late pregnancy as is the case in women with type 1 diabetes." (PMID 31828161, 2019). "The effects of repeated O3 exposure on adipose tissue inflammation and insulin release but not insulin sensitivity were also observed in another model of obese type 2 diabetes, KKAy mice." (PMID 31867021, 2019). "Protein tyrosine phosphatase 1B (PTP1B) is considered a potential target for the treatment of type II diabetes and obesity due to its critical negative role in the insulin signaling pathway." (PMID 30729132, 2019). "In conclusion, we have found that in early type 2 diabetes there are no ethnic differences in insulin sensitivity between BAM and WEM despite BAM having lower visceral fat and higher skeletal muscle mass." (PMID 30729259, 2019). "Libre Pro can improve HbA1c and treatment satisfaction without increasing hypoglycaemic exposure in insulin-treated type 2 diabetes individuals managed in primary/secondary care centres." (PMID 31271312, 2019). "Type I diabetes mellitus, which depends on insulin, most often occurs in young people, while type II diabetes mellitus, which does not depend on insulin, usually develops in the aged." (PMID 31281410, 2019). "Type 2 diabetes mellitus (T2DM), characterized by chronic hyperglycemia resulted from resistance against insulin, is the most prevalent metabolic disorder worldwide, and it currently affects over 300 million people all over the world (American Diabetes Association, 2014; Zheng, Ley, & Hu, 2018)." (PMID 30811895, 2019). "Their mechanism of action is independent of insulin, thus allowing their use in any stage of type 2 diabetes." (PMID 31198610, 2019). "The incidence of type-2 diabetes increases in older individuals primarily due to age-related declines in beta cell function and impaired insulin secretion, rather than to insulin resistance." (PMID 30865634, 2019). "The results are difficult to compare with the literature data, since the plasma profile of omentin-1 expression in obese patients with type 2 diabetes subjected to an insulin mix therapy has not been assessed so far." (PMID 31195747, 2019). "Despite quite numerous publications regarding the role of analyzed adipocytokines in type 2 diabetes, there are no data investigating the effect of insulin mixture therapy on plasma levels of these molecules." (PMID 31195747, 2019). "Our group has studied the separate and combined effects of GIP, GLP-1 and GLP-2 (the latter known to be glucagonotropic but without any notable effect on insulin secretion) on glucagon secretion in 10 patients with type 2 diabetes." (PMID 31443356, 2019). "We demonstrated that in most existing algorithms aimed at calculating prandial insulin doses in type 1 diabetes only carbohydrates are counted, whereas in type 2 diabetes the meal content is often not taken into consideration." (PMID 30871141, 2019). "Participants with type 2 diabetes not using insulin had blood glucose values within target range (70-180 mg/dL) 89% of the time." (PMID 31593545, 2019). "Of these participants, 38% did not receive insulin at diagnosis, of whom 47% self-reported type 2 diabetes." (PMID 30969375, 2019).
type 2 diabetes (continued). "Current treatment options are limited to lifestyle modifications, non-specific drugs, or insulin injections for those with type 2 diabetes." (PMID 31024226, 2019). "In type 2 diabetes (adult onset diabetes), the pancreas makes insulin, however, it either would not produce enough, or the insulin does no longer work properly." (PMID 31663031, 2019). "Inflammation may play a role in the pathogenesis of type 2 diabetes, COX generates prostaglandins, which negatively modulate glucose-stimulated insulin secretion." (PMID 31735164, 2019). "For this reason, we selected patients with type 2 diabetes, who were using basal–bolus regimens so that one study can be done with and another without pre-meal short-acting insulin." (PMID 31119456, 2019). "The evidence to date suggests that this is mediated via altered insulin secretion although this was not confirmed in the most recent type 2 diabetes GWAS where the postulated mechanism of action for KCNQ1 was designated unclassified." (PMID 30641161, 2019). "Peschke and colleagues have shown a negative correlation between melatonin and insulin levels in patients with type 2 diabetes." (PMID 31970309, 2019). "In this study, we assessed the development of the barrier function of type 2 diabetic patient-derived hiPSC-RPEs assessed under different glucose concentrations in the presence or absence of added insulin." (PMID 31375001, 2019). "The frequency of the T allele in non‐diabetic control participants, type 2 diabetes patients with insulin treatment and type 2 diabetes patients without insulin treatment was found to be 0.42, 0.42 and 0.43, respectively." (PMID 30970177, 2019). "Antidiabetic medication: the drugs used by patients with type 2 diabetes at admission were dominated by glucose-lowering drugs (74%; OADs and GLP-1 receptor agonists) and insulin (25%), 77% of these patients receiving GLDs as add-on medication, while only 20% were on a diet alone." (PMID 31830073, 2019). "Participants with type 2 diabetes not using insulin showed no significant improvements for BG time in range." (PMID 31593545, 2019). "The study by Hermanns showed the difference in the proportion of individuals with type 1 and 2 diabetes without insulin treatment and those with type 2 diabetes with insulin treatment who were diagnosed with clinical and subclinical depression." (PMID 31726788, 2019). "In non-diabetic individuals, GIP potentiates postprandial insulin secretion, but this effect is severely diminished or even absent in people with type 2 diabetes." (PMID 31443356, 2019). "Blood glucose decreases during and after exercise for individuals with type 2 diabetes; however, this does not usually result in hypoglycaemia unless the individual is taking insulin or sulphonylureas." (PMID 31161377, 2019). "The findings reported herein show that BACH2 rs3757247 was significantly more frequent in the six patients with insulin‐triggered type 1 diabetes than in non‐diabetic control participants and type 2 diabetes patients with or without insulin treatment." (PMID 30970177, 2019). "Hyperglycemia, insulin resistance, and relative lack of insulin were key features of Type-2 Diabetes Mellitus (T2DM)." (PMID 31693691, 2019). "Current reports show that the major pathophysiology of type 2 diabetes in underweight/normal weight individuals is rapid beta cell failure as opposed to insulin resistance." (PMID 31673340, 2019). "Although biosimilar insulin therapy is not uncommon in Asia, only one-third of patients with type 2 diabetes in Asia and 7.4% of patients with type 2 diabetes in Taiwan achieve HbA1c < 7.0% (53 mmol/mol) after 6 months of basal insulin therapy." (PMID 31415655, 2019). "The first significant factor identified was the duodenal glucose-dependent insulinotropic polypeptide, GIP, which however, turned out not to stimulate insulin secretion in patients with type 2 diabetes." (PMID 31080438, 2019).
type 2 diabetes (continued). "The FXR agonist, obeticholic acid (OCA), improves insulin sensitivity in patients with type 2 diabetes with nonalcoholic fatty liver disease." (PMID 31237448, 2019). "To date, type 2 diabetes is considered to be a “bi-hormonal disorder” rather than an “insulin-centric disorder,” suggesting that glucagon is as important as insulin." (PMID 31357734, 2019). "Half of participants were lean and obese, physician diagnosed with type 2 diabetes, not using insulin, and undergoing standard medical care." (PMID 31275881, 2019). "According to our knowledge, there are no previous publications in which the maturation of hiPSC-RPEs derived from type 2 diabetics and healthy controls have been assessed in high or normal glucose concentration in the presence or absence of added insulin." (PMID 31375001, 2019). "The recent SITA-HOSPITAL randomized controlled study investigated 279 noncritical care patients with type 2 diabetes and showed that oral sitagliptin plus basal insulin led to similar glycemic control than the more labor-intensive basal–bolus insulin regimen." (PMID 31261760, 2019). "Type 2 diabetes (T2D) is a chronic condition that affects how our body metabolizes sugar or glucose, inducing either resistance to the effects of insulin, or lack of its production in a way sufficient to maintain normal glucose levels." (PMID 33693353, 2019). "Type 2 diabetes (T2DM) is a progressive disease and although glycaemic control can initially be achieved with the use of other anti-hyperglycaemic agents, a large proportion of people will eventually require insulin to achieve glycaemic targets." (PMID 31796048, 2019). "In contrast, older adults suffering from obesity and/or type 2 diabetes appear to be more sensitive to increases in skeletal muscle GLUT4 protein content, which could contribute to their improved insulin sensitivity with resistance training." (PMID 31684154, 2019). "Although the mechanisms are not fully elucidated, defects in insulin action and hyperglycemia have been shown to alter plasma levels of lipoprotein in patients with type 2 diabetes." (PMID 30944035, 2019). "We hypothesised that, in those with early type 2 diabetes, black (West) African men (BAM) have greater hepatic and adipose tissue insulin sensitivity, compared with white European men (WEM), because of their reduced visceral fat." (PMID 30729259, 2019). "It was also reported that the lipid content in hepatocytes was decreased by intranasal administration of INS in lean healthy subjects, but not in patients with type 2 diabetes." (PMID 30274197, 2018). "The safety and efficacy of Gla-300 compared with Gla-100 was investigated in 1689 participants with type 2 diabetes receiving concomitant OADs in the EDITION 2 (background therapy basal insulin + OAD) and EDITION 3 (background therapy OAD only, insulin-naïve) studies." (PMID 29370218, 2018). "Recently, liver triglyceride production in type-2 diabetes was shown to be dependent on FFA levels rather than circulating insulin levels." (PMID 29339795, 2018). "Insulin infused at high, intermediate and low doses neither affected the level of undercarboxylated osteocalcin in participants with type 2 diabetes nor in healthy individuals." (PMID 30057568, 2018). "Understanding what is happening in the pancreas is the key to type 2 diabetes, as the condition never occurs without a major decrease in acute insulin secretion." (PMID 29143063, 2018). "High-quality RCTs investigating the role of structured education in those with insulin-treated type 2 diabetes are generally lacking and even fewer have reported rates of severe hypoglycaemia." (PMID 28660491, 2018). "It is not clear that the 7,000,000 insulin users with type 2 diabetes in the US, who are generally older than the average insulin user with type 1 diabetes, would be willing to adopt the complexity of using an insulin pump and a CGM." (PMID 29682315, 2018).
type 2 diabetes (continued). "In another small study, all Type 2 diabetes patients (n = 12) no longer required insulin therapy at 12 months post-surgery, and miR-320a changed significantly." (PMID 30687230, 2018). "However, clinical trials with higher CPAP adherence in patients with either type 2 diabetes or prediabetes have found that therapeutic CPAP improves glycemic control or insulin sensitivity compared to the control group." (PMID 30042734, 2018). "Type 2 Diabetes Mellitus (T2DM) is a multifactorial metabolic disease that occurs with fasting blood glucose concentrations above 120 mg/dL (>7 mM), due to the abnormal pancreatic β-cells and/or insulin resistance." (PMID 29415496, 2018). "Pancreatic binding of [11C/3H]AZ12204657 was co-localized with insulin-positive islets of Langerhans in non-diabetic individuals and individuals with type 2 diabetes (T2D)." (PMID 30588560, 2018). "Elucidation of the interaction of AMPK and insulin signalling, and their roles in FAK regulation, may lead to novel therapeutic strategies for chronic diseases as seemingly disparate as type 2 diabetes and cancer." (PMID 29022062, 2018). "The transport of INS into the brain across BBB is decreased with obesity and type 2 diabetes most likely to protect the brain from certain substances that could modulate metabolism and to maintain brain homeostasis." (PMID 30274197, 2018). "This study synthesized high-quality evidence about the level of OHA adherence in Type 2 diabetics who are not using insulin and identified factors affecting OHA adherence in the Saudi population." (PMID 30533042, 2018). "Elevated levels of lipid metabolites such as DAGs and ceramides have been observed in skeletal muscle from obese and subjects with type 2 diabetes mellitus, and it is proposed that ceramide, DAG and long-chain FA acyl-CoA may interfere with insulin signalling." (PMID 30510272, 2018). "Human intervention studies fail to show benefit in type 2 diabetes and insulin resistant non-diabetic people, whereas observational studies in humans seems to be encouraging." (PMID 29538286, 2018). "Second, in KCNJ11 permanent neonatal diabetes, high-dose sulfonylureas facilitate the response to alternative pathway stimuli and do not directly stimulate insulin secretion as in type 2 diabetes." (PMID 29880308, 2018). "Because insulin exerts the inhibitory effects on gene expression for SELENOP in the hepatocytes, impaired insulin action in fatty liver or type 2 diabetes may up-regulate SELENOP production in the liver." (PMID 30425271, 2018). "Sub-cellular network analysis demonstrated the metabolites shared biological significance underlying canonical signaling pathways such as insulin, AMPK, PI3-Akt, and type 2 diabetes signaling pathway, but not ADMA." (PMID 29391561, 2018). "Basal insulin plus oral hypoglycemic agents (OHAs) has not been investigated for early intensive antihyperglycemic treatment in people with newly diagnosed type 2 diabetes." (PMID 30420969, 2018). "Insulin therapy is often needed to overcome insulin receptor resistance in type 2 diabetes; however, the impact of providing additional insulin to already hyperinsulinemic subjects is not clear." (PMID 30249002, 2018). "This study is aimed at specifically quantifying the direct effects of vitamin D supplementation on indexes of glucose and insulin homeostasis as well as incidence of type 2 diabetes (T2D) among nondiabetic adults." (PMID 30627160, 2018). "A 2-week treatment with AZP-531 improved glucose concentrations, without increasing insulin levels, suggesting an insulin sensitizing effect, and decreased body weight in overweight/obese subjects while patients with Type 2 diabetes had their HbA1c reduced." (PMID 29320575, 2018). "To address this issue, we assessed human serum IgG isotypes (IgG1, IgG2, IgG3, and IgG4) in non-diabetic offspring of type 2 diabetic individuals and correlated their concentration with insulin sensitivity assessed using the euglycemic hyperinsulinemic clamp." (PMID 30206293, 2018).